BRCA2 (BRCA2 DNA repair associated)
Diseases named in the same sentence as BRCA2 in open-access papers (continued):
Sharing a sentence is not in itself a finding about the gene and the disease.
breast cancer (continued). "The characterization of BRCA1 and BRCA2 founder mutations and association between the founder mutations and breast cancer risk should be studied in a large-scale Chinese population size." (PMID 26852015, 2016). "Compared with women without mutations, those with somatic mutations in BRCA1 and BRCA2 genes are at increased risk for the development of breast cancer (life time breast cancer risk of 50–80%)." (PMID 27149669, 2016). "The frequently observed VNTR association with in BRCA1+ and BRCA2+ breast cancer group indicates that VNTR polymorphism in the XRCC5 promoter is associated with altered risk of breast cancer in BRCA1+ and BRCA2+ carriers." (PMID 27148484, 2016). "Suggestion of an association between BRCA2 c.7806-2A > G and risk of breast cancer in males has emerged." (PMID 26852130, 2016). "BRCA1 and BRCA2 mutations account for approximately 16% of the familial risk of breast cancer and are also associated with increased risk of pancreatic, stomach, laryngeal, fallopian tube and prostate cancer." (PMID 27037238, 2016). "By contrast, 77% of breast tumours arising in BRCA2 mutation carriers are ER-positive and only 16% are found to be triple negative, paralleling the breast cancer subtypes seen in the general population." (PMID 27881737, 2016). "The BRCA2 variant (V2109I) was found in a patient with breast cancer (BC) with family history of pancreas cancer and a patient with esophageal cancer with family history of gastric cardia cancer." (PMID 27701467, 2016). "The same gene deletion (referred by the Breast Cancer Information Core as 1983del5) has even been reported as a familial BRCA2 mutation." (PMID 27165126, 2016). "Germline mutations in the BRCA2 gene increase the lifetime risk of developing breast cancer by up to 66% and ovarian cancer by approximately 12%." (PMID 27881737, 2016). "Patients harboring inactivating mutations in BRCA1 or BRCA2 are at an increased risk of developing breast cancer." (PMID 27323902, 2016). "In Part 2 BRCA1- or BRCA2-mutated HER2-negative breast cancer patients will be randomized between standard capecitabine 1250 mg/m2 BID day 1–14 q day 22, versus 2 cycles carboplatin-olaparib followed by olaparib monotherapy 300 mg BID." (PMID 27323902, 2016). "Multiple breast cancer susceptibility genes such as BRCA1 and BRCA2 with high penetrant disease-associated mutations have been shown to segregate in families with breast cancer by linkage studies." (PMID 27806084, 2016). "To date, over 3.000distinct germline mutations, polymorphisms and sequence variants have been described inBRCA1 and BRCA2, spread throughout both genes(Breast Cancer Information Core, BIC, 2014).Most are point mutations, small insertions or deletions." (PMID 27223485, 2016). "RAD51 plays a central role in DNA repair by forming a complex with BRCA2, but its overexpression in breast cancer has been found to be associated with poor prognosis." (PMID 27959953, 2016). "Large genomic rearrangements account for 4–28 % of all BRCA1 and BRCA2 mutations, and such mutations have been found in Chinese women at a high risk for breast cancer." (PMID 26852015, 2016). "More recent and larger studies in Israel, Italy and USA described prevalences of 8%, 7%, and 16%, respectively, of BRCA2 mutations in male breast cancer patients." (PMID 27532258, 2016). "We report on a young patient who is a BRCA2 mutation carrier diagnosed with HER2-positive breast cancer with visceral and brain metastases." (PMID 27195161, 2016). "The complete coding regions of the BRCA1 and BRCA2 genes were screened for small-range mutations and large genomic rearrangements in all 523 breast cancer patients." (PMID 27553291, 2016). "6.5 % were overly reassuring and 0.6 % would have said a BRCA2 mutation contributed to causing the breast cancer." (PMID 26608569, 2015). "Note that here, used a reference sample because there are three groups of interest: BRCA1 mutation, BRCA2 mutation, and sporadic cases of breast cancer." (PMID 25910040, 2015).
breast cancer (continued). "We determined the BRCA1 and BRCA2 status in these cases and report the identification of several rare variants that can potentially explain breast cancer susceptibility in each case analyzed." (PMID 25923920, 2015). "With regards to genetics, PALB2 (Partner And Localizer of BRCA2) was presented as a new high-risk breast cancer gene identified and the reasons why it should be added to genetic testing for BRCA1/BRCA2 were clearly explained." (PMID 25729421, 2015). "Our study reaffirms that specific BRCA1 and BRCA2 mutations found previously to recur in French Canadian breast cancer and breast-ovarian cancer families, also recur in women with ovarian cancer not selected for family history of cancer." (PMID 25884701, 2015). "Female BRCA1 or BRCA2 gene mutation carriers have an increased risk of developing breast cancer of 27–88 %, and a maximum lifetime risk of developing ovarian cancer of 6–59 %." (PMID 25700605, 2015). "It has previously been reported that mutations in BRCA1 and BRCA2 genes are linked to breast cancer." (PMID 25885115, 2015). "Germ line mutations of BRCA2 are associated with not only an increased risk of breast cancer and ovarian cancer but also with prostate cancer and pancreatic cancer." (PMID 26082817, 2015). "In the main effect analysis, rs6064391 showed a suggestion of association with reduced breast cancer risk in BRCA2 mutation carriers: HR = 0.87, unadjusted p = 0.036." (PMID 25830658, 2015). "The significance of the RAD51 polymorphism rs1801320 has been best characterized in patients with breast cancer, especially in carriers of BRCA2 gene mutations." (PMID 26339569, 2015). "We estimated the risk of breast cancer for individuals with the T1a1 haplogroup compared with individuals with another T subclade haplogroup in the population of BRCA2 mutation carriers using a more classical statistical method, a weighted Cox regression." (PMID 25925750, 2015). "Individuals carrying pathogenic mutations in the BRCA1 and BRCA2 genes have a high lifetime risk of breast cancer." (PMID 25925750, 2015). "Germline mutations in BRCA1 and BRCA2 genes are associated with familial breast cancer risk in women, although the majority of breast cancers are sporadic in nature." (PMID 29061935, 2015). "In support of this notion, we previously showed loss of heterozygosity, a mechanism of BRCA2 inactivation, in a canine mammary tumor sample." (PMID 26202431, 2015). "Using the best-evidence synthesis, there was indecisive evidence for an association between BRCA2 mutation carriership and unadjusted overall survival of breast cancer patients." (PMID 25816289, 2015). "Over the last decade the discovery of genetic testing for breast cancer susceptibility genes (such as BRCA1 & BRCA2) has seen a rise in preemptive screening in many countries, particularly where a strong family history of breast cancer has been observed." (PMID 26010605, 2015). "Together BRCA1 and BRCA2 mutations account for about 20–25% of all inherited breast cancers, and BRCA1/2-mutation carriers face a high risk of developing breast cancer." (PMID 25531315, 2015). "As ILC risk is close to the overall breast cancer risk seen in carriers of BRCA1/BRCA2 mutations, it seems reasonable to offer the same type of surveillance as a routine procedure, and start screening at age 30 years with annual MRI and mammogram." (PMID 25848941, 2015). "This is the basis for the concept that PARP inhibitors induce synthetic lethality in HR repair deficient tumors and provides a novel strategy for cancer therapy, at least in breast cancer patients who have mutations in BRCA1 or BRCA2." (PMID 25769025, 2015). "In this study, we explored mitochondrial haplogroups as potential modifiers of breast cancer risk in women carrying pathogenic BRCA1 or BRCA2 mutations." (PMID 25925750, 2015).
breast cancer (continued). "Standard clinical factors predicted both BRCA mutation status (BRCA1 and BRCA2), notably the number of breast cancers occurring before 50 years and ovarian cancers." (PMID 26047126, 2015). "Women carrying a germline BRCA1 mutation have a 57–65% chance of developing breast cancer before the age of 70 years, which for BRCA2 mutation carriers is 45–55%." (PMID 26000714, 2015). "For instance, women with defective HR genes BRCA1 and BRCA2 have a significantly increased risk of developing breast cancer or ovarian cancer." (PMID 25374063, 2015). "An impressive number of studies have already been conducted to address the association between BRCA1 and/or BRCA2 mutation carriership and breast cancer survival." (PMID 25816289, 2015). "Previous studies showed that breast cancer has an inherited component, and the high-penetrance breast cancer predisposing genes, BRCA1 and BRCA2, account for up to 10–40 % of inherited breast cancer." (PMID 26489409, 2015). "Variation in CSTF1, located next to AURKA, was also found to be associated with breast cancer risk in BRCA2 mutation carriers: rs2426618 per-allele HR = 1.10, 95% CI 1.03 – 1.16, p = 0.005 (FDR-adjusted p = 0.045)." (PMID 25830658, 2015). "In fact, the prevalence of high penetrance breast cancer genes in our cohort was <1 % among those tested for BRCA1/BRCA2 mutations." (PMID 26673874, 2015). "Germ-line mutations in several genes, such as BRCA1 and BRCA2, are known to increase the risk of breast cancer." (PMID 26468334, 2015). "Following on these observations, we further assessed the link between the AURKA-HMMR-TPX2-TUBG1 functional module and risk of breast cancer in BRCA1 or BRCA2 mutation carriers." (PMID 25830658, 2015). "A cohort of BRCA1 and BRCA2 mutation carriers >18 years old who underwent surgery for breast cancer at an academic hospital (1992–2011) and had pathology available for review were included for study." (PMID 26496879, 2015). "In 5%–10% patients, inherited mutations in highly penetrant cancer susceptibility genes, such as BRCA1 and BRCA2, are known to confer a significantly elevated risk (>10-fold) of breast cancer and their carrier relatives." (PMID 27600231, 2015). "Although deleterious BRCA1 and BRCA2 mutations constitute the most common breast cancer syndrome, they explain the genetic background in only 1–3 % in sporadic breast cancer populations and about 15 % of familial breast cancer." (PMID 26082817, 2015). "In total we detected 13 BRCA1/2 mutations in our study cohort of 108 patients (12 %; 95 % CI = 6.6–19.7 %), thus reinforcing the important contribution of germline BRCA1 and BRCA2 mutations to inherited breast cancer in this mixed South Africa cohort." (PMID 26577449, 2015). "Two individuals (UTSW9 and UTSW36) harbored nonsense mutations in PALB2, which has recently been reported to result in an elevated risk for breast cancer similar to BRCA2 mutations." (PMID 26023681, 2015). "Consistent with the main analysis, the competing risk model showed an rs2426618 association with breast cancer risk only in BRCA2 mutation carriers (p = 0.002)." (PMID 25830658, 2015). "Our results reaffirm that specific BRCA1 and BRCA2 mutations found previously to recur in French Canadian breast cancer and breast-ovarian cancer families, also recur in women with ovarian cancer not selected for family history of cancer." (PMID 25884701, 2015). "It is estimated that approximately 10% of men with breast cancer have a genetic predisposition, with BRCA2 being the most prevalent genetic mutation." (PMID 25632310, 2015). "In humans, inheritable breast cancers have been linked with mutations in the breast cancer susceptibility gene, breast cancer 2 early onset (BRCA2), and the lifetime risk of developing breast cancer is high (81–88 %) in females carrying a BRCA2 mutation." (PMID 26202431, 2015).
breast cancer (continued). "In contrast, the proportion of ILCs in BRCA2 mutation carriers was 8.4%, closer to the characteristics of breast cancers from the general population." (PMID 25848941, 2015). "The BRCA2 mutation (Asn372His) is weakly associated with an increased chance of breast cancer but its incidence in some parts of the world is high." (PMID 26102504, 2015). "Recently, the discovery of some miRNAs regulating BRCA2 expression levels were linked to breast cancer development in humans." (PMID 26202431, 2015). "Because this medulloblastoma had an oncogenic mutation in BRCA2 (6174delT), we also tested its in vitro response to a PARP1 inhibitor, thought to induce synthetic lethality in BRCA2-mutated breast cancer." (PMID 26380221, 2015). "Germ-line mutations in the BRCA1 or BRCA2 genes are the most common causes of breast cancer predisposition resulting in a 70% and 60% lifetime risk of developing breast cancer, respectively." (PMID 26378051, 2015). "Recently, the breast cancer 2 early onset (BRCA2) gene was proposed to be associated with tumorigenesis in dogs." (PMID 26202431, 2015). "In a recent prospective analysis, contralateral RRM was found to be associated with improved overall survival in BRCA1 or BRCA2 mutation carriers with a prior primary breast cancer (PBC)." (PMID 26669313, 2015). "Germline mutations in the BRCA1 and BRCA2 genes account for 20–25 % of inherited breast cancers and about 10 % of all breast cancer cases." (PMID 26543556, 2015). "Mutations in genes such as BRCA1 and BRCA2 lead to autosomal dominant inherited cancer susceptibility and confer a high lifetime risk of breast cancer, as well as ovarian and other cancers." (PMID 26577449, 2015). "Nevertheless, the combined frequency of BRCA1 and BRCA2 mutations in the general populations is nearly 0.5%; thus, more common variants are more relevant for determining predisposition to breast cancer." (PMID 25339628, 2015). "The discovery of the BRCA1 and BRCA2 genes as major breast cancer susceptibility genes led to great advances in the genetic screening for the disease and the understanding of its inheritance." (PMID 25923920, 2015). "Mutations in BRCA1 and BRCA2 are associated with an increased risk of breast cancer, and is reported to be as high as 80 %, and also associated with ovarian, prostate, pancreatic and male breast cancer." (PMID 26468334, 2015). "(2002) revealed a 96% risk reduction in ovarian cancer and a 53% risk reduction in breast cancer in 551 women with a BRCA1 or BRCA2 mutation." (PMID 26557407, 2015). "The patients with BRCA2-associated breast cancer had an average age at diagnosis of 46.7 years (range 21 - 66) in the first cohort, and 45.8 years (range 27 - 67) in the second cohort." (PMID 26378051, 2015). "The designation of the K3326* truncating variant in exon 27 of BRCA2 as a breast cancer predisposing allele has changed over time as new evidence has emerged." (PMID 26455428, 2015). "We next performed a mutation analysis of the BRCA2 promoter region in the canine mammary tumor samples." (PMID 26202431, 2015). "The results show that mutations in PALB2 are rare, but along with BRCA1 and BRCA2 are key breast cancer susceptibility genes in the Xinjiang region of China." (PMID 26489409, 2015). "Other missense mutations were found in tumor suppressor genes, including the susceptibility gene for breast cancer BRCA2 (n = 6) or the RAS family negative regulator NF1 (n = 1)." (PMID 26155992, 2015). "A study of 564 French Canadian women with breast cancer under 50 years of age reported a 4.8% carrier frequency in a mutation screen for eight BRCA1/BRCA2 mutations found to recur in French Canadian HBC/HBOC cancer families." (PMID 25925845, 2015). "BRCA testing had previously demonstrated a deleterious heterozygous germline BRCA2 6174delT frameshift mutation in the mother and in her sister who had breast cancer." (PMID 26380221, 2015).